CDKN2B-AS1 (CDKN2B and CDKN2A antisense cis and trans regulatory RNA 1)
Synonyms: ANRIL; RP11-145E5.4; NCRNA00089; p15AS; CDKN2B-AS; PCAT12; 66CTG; CDKN2BAS
Gene: Long non-coding RNA gene on chromosome 9 (21,994,139 to 22,212,895, forward strand). Ensembl gene ENSG00000240498.
Gene Ontology:
Biological process: heterochromatin formation
Diseases named in the same sentence as CDKN2B-AS1 in open-access papers:
CDKN2B-AS1 is named in the same sentence as 198 diseases in open-access papers, as found by Europe PMC text mining. Sharing a sentence is not in itself a finding about the gene and the disease. The quoted sentences say what the papers report.
atherosclerosis (120 papers, 2009 to 2025). A disease characterized by the build-up of fatty material and calcium deposition in the arterial wall resulting in partial or complete occlusion of the arterial lumen. "Moreover, studies have highlighted variants in CDKN2B-AS1 (ANRIL) and identified a relationship with atherosclerosis." (PMID 30926762, 2019). "This risk allele was shown to be associated to the linear form of the non-coding RNA CDKN2B-AS1 (CDKN2B Antisense RNA 1, alias ANRIL) gene while a circular form may control rRNA maturation in vascular smooth muscle cells and macrophages and protect from atherosclerosis." (PMID 36247456, 2022). "ANRIL (Antisense Noncoding RNA in the INK4 Locus), also named CDKN2B-AS1, is a long non-coding RNA with outstanding functions that regulates genes involved in atherosclerosis development." (PMID 38003316, 2023). "With “atherosclerosis” as the key word retrieved in NONCODE, H19, ANRIL, and CDKN2B-AS1 were found to be involved in atherosclerosis onset." (PMID 30778327, 2019).
coronary artery disease (86 papers, 2009 to 2025). "Specifically, the variant rs3217986, mapped on CDKN2B-AS1 (ANRIL), has been associated with cutaneous melanoma and coronary artery disease." (PMID 37834450, 2023). "Recently, a risk haplotype at the ANRIL/CDKN2B-AS1 locus on chromosome 9p21.3, that is not only associated with coronary artery disease / myocardial infarction (CAD/MI) but also with PD, could be identified by genome-wide association studies." (PMID 29868613, 2018).
diabetes (46 papers, 2009 to 2025). "Another lncRNA, CDKN2B-AS1 (ANRIL), has also been linked to cancer, diabetes, and cardiovascular diseases." (PMID 30909482, 2019).
lung cancer (42 papers, 2014 to 2025). A malignant neoplasm involving the lung. "In this study, the variant rs62560775, found on CDKN2B-AS1 (ANRIL), is linked to lung cancer." (PMID 37834450, 2023). "Furthermore, three CDKN2BAS1 spliced variant transcripts expressed in lung cancer cell lines have been shown to have various enhancer activities." (PMID 24681604, 2014). "In this context, numerous studies have demonstrated the oncogenic properties of the long non-coding RNA CDKN2B-AS1 (CDKN2B antisense RNA 1, ANRIL) in multiple carcinomas, including thyroid cancer, gastric cancer, and lung cancer." (PMID 40149464, 2025). "ANRIL: ANRIL, also known as CDKN2B-AS1, is a well-characterized lncRNA implicated in COPD and lung cancer pathogenesis." (PMID 39201688, 2024). "Concurrently, we observed cell type–specific effects for lung cancer with two variants located in cancer pleiotropic regions (TERT and risk of lung adenocarcinoma and CDKN2BAS1 with risk of lung SCC), indicating distinct etiological processes for these two subtypes." (PMID 24681604, 2014).
myocardial infarction (42 papers, 2012 to 2025). Gross necrosis of the myocardium, as a result of interruption of the blood supply to the area, as in coronary thrombosis. "Variants in the 9p21 region, which includes CDKN2B-AS1 (ANRIL) and CDKN2A/B, were also associated (lead SNP rs1556516, 49.8% frequency, p=4.7×10−16); this locus is involved in cellular senescence and associated with myocardial infarction and peripheral vascular disease." (PMID 29227965, 2017). "For example, CDKN2B-AS1 (or ANRIL) and MALAT1 can be used to predict the development of left ventricular dysfunction as ANRIL was expressed at lower levels and MALAT1 expression was higher in patients with myocardial infarction than in healthy volunteers." (PMID 34940525, 2021).
gastric cancer (39 papers, 2014 to 2025). A primary or metastatic malignant neoplasm involving the stomach. "Here, we reported that ANRIL (CDKN2B-AS1), a 3.8-kb long noncoding RNA, recruiting and binding to PRC2, was generally upregulated in human gastric cancer (GC) tissues." (PMID 24810364, 2014).
type 2 diabetes (33 papers, 2010 to 2025). "Recent studies have shown that SNPs (rs3217992; rs1063192, and rs1333049) in lncRNA, ANRIL (also known as CDKN2BAS or CDKN2B-AS1) are linked to various physiological and pathological states, such as cardiovascular disease, type 2 diabetes and AD." (PMID 29719633, 2018). "Parental lifespan-associated variants included rs1556516, located in an intron of CDKN2B-AS1 (ANRIL), a long non-coding RNA; variants in this region, 9p21.3, have previously been associated with CAD, type-2 diabetes, and cancer." (PMID 29227965, 2017). "Compared to control subjects, expression levels of lncRNAs in PBMCs from type 2 diabetes patients showed significantly (p < 0.05) increased levels of HOTAIR, MEG3, LET, MALAT1, MIAT, CDKN2BAS1/ANRIL, XIST, PANDA, GAS5, Linc-p21, ENST00000550337.1, PLUTO, and NBR2." (PMID 30139387, 2018). "Compared to control subjects, expression profiling of lncRNAs in PBMCs from type 2 diabetes patients showed significantly (p < 0.05) increased levels of HOTAIR, MEG3, LET, MALAT1, MIAT, CDKN2BAS1/ANRIL, XIST, PANDA, GAS5, Linc-p21, ENST00000550337.1, PLUTO, and NBR2." (PMID 30139387, 2018).
prostate carcinoma (32 papers, 2013 to 2023). A carcinoma that arises from epithelial cells of the prostate gland. "The prostate cancer risk-associated variant at this locus, rs17694493, is predicted to disrupt the binding motifs of transcription factors STAT1 and RUNX1 and positioned in the intronic region of a novel lncRNA gene CDKN2B-AS1 (also known as ANRIL)." (PMID 34946977, 2021).
periodontitis (27 papers, 2009 to 2025). An acute or chronic inflammatory process that affects the tissues that surround and support the teeth. "Genetic locus cyclin-dependent kinase inhibitor 2B antisense 1 (CDKN2B-AS1) RNA, known as ANRIL (chromosome 9, p21.3), has consistently been reported in genome-wide association studies (GWAS) to be associated with periodontitis." (PMID 40810409, 2025).
osteosarcoma (15 papers, 2017 to 2025). A usually aggressive malignant bone-forming mesenchymal neoplasm, predominantly affecting adolescents and young adults. "The lncRNA ANRIL (also known as CDKN2B-AS1) was first identified from familial melanoma patients with a large germline deletion in the INK4B-ARF-INK4A gene cluster, and has been previously characterized as an oncogene in osteosarcoma and other cancer types." (PMID 34681828, 2021).
intracranial aneurysm (12 papers, 2012 to 2023). "CDKN2BAS1/ANRIL, located in the 9p21 chromosomic region, has been reported in numerous studies as a genetic risk locus for CAD, intracranial aneurysms and diverse cardiometabolic disorders." (PMID 35234888, 2022).
endometriosis (11 papers, 2010 to 2025). The growth of functional endometrial tissue in anatomic sites outside the uterine body. "Uno and colleagues reported that rs10965235, locating in an intron of ANRIL (antisense non-coding RNA in the INK4 locus or CDKN2B-AS1) on chromosome 9p21, was significantly associated with endometriosis in Japanese population." (PMID 27055116, 2016). "We found 11 loci showing nominal association (P < 1.0 × 10−6), 3 of which were established endometriosis loci (WNT4, CDKN2BAS1, ID4) and 8 had not previously been reported." (PMID 28333195, 2017).
glaucoma (8 papers, 2012 to 2025). Increased pressure in the eyeball due to obstruction of the outflow of aqueous humor. "Background/Objectives: The INK4 locus at chromosome 9p21.3, encoding CDKN2A, CDKN2B and the long non-coding RNA CDKN2B-AS1 (ANRIL), has been implicated in multiple diseases, including glaucoma and cardiovascular disease." (PMID 40722690, 2025).
psoriasis (5 papers, 2020 to 2025). An autoimmune condition characterized by red, well-delineated plaques with silvery scales that are usually on the extensor surfaces and scalp. "The CDKN2B-AS1 (ANRIL) locus demonstrates multiple psoriasis-associated variants, most of which are associated with a higher risk for psoriasis, while the rs4977574 appears to confer protective effects against the disease." (PMID 40981386, 2025).
aneurysm (3 papers, 2017 to 2023). Bulging or ballooning in an area of an artery secondary to arterial wall weakening.
diabetic cardiomyopathy (2 papers, 2022 to 2023). Diabetic cardiomyopathy is a disorder of the heart muscle in people with diabetes. "The antisense RNA to INK4 locus (ANRIL; also known as CDKN2B-AS1) gene gives rise to a 3.8-kb lncRNA that is prominently deregulated in many diseases, including diabetic cardiomyopathy and nephropathy." (PMID 35464068, 2022).
prostate tumour (2 papers, 2017 to 2020). "CDKN2B-AS1, also known as ANRIL, is induced in prostate tumour tissue and could be another explanation for low RBMS1 abundance in PCa30." (PMID 33093529, 2020).
cancer (149 papers, 2010 to 2025). A tumor composed of atypical neoplastic, often pleomorphic cells that invade other tissues. "CDKN2B-AS1 (ANRIL) is also a captivating lncRNA with implications in various cancer types, where it serves as a critical regulator of cell proliferation." (PMID 37834450, 2023). "CDKN2B antisense RNA 1 (CDKN2B-AS1), also known as ANRIL, was on the top of this list (i.e., cancer related EAC-specific prognostic lncRNAs), however, only three studies have addressed its association with esophageal cancer." (PMID 32024523, 2020). "In this review, we focused on the implication of the lncRNA ANRIL (Antisense Noncoding RNA in the INK4 Locus, CDKN2B-AS1) in cancers." (PMID 37627188, 2023). "Five CDKN2B‐AS1 SNPs, including rs564398, rs1333048, rs1537373, rs2151280 and rs8181047, were analysed in 1060 OSCC cases and 1183 cancer‐free controls." (PMID 37724356, 2023). "The up-regulation of lincRNA ANRIL, also called CDKN2B antisense RNA 1 (CDKN2B-AS1),has been described in many different cancers and correlated with tumor progression." (PMID 34204634, 2021). "The carcinogenicity of lncRNA ANRIL (CDKN2B-AS1) has been confirmed in various studies, and the binding of lncRNA P14AS and AUF1 can increase the levels of ANRIL, resulting in cancer cell proliferation." (PMID 34778084, 2021).
tumor (120 papers, 2010 to 2026). "The locus also encodes CDKN2B-AS1, also known as ANRIL, a long non-coding RNA spanning over 126 kb and overlapping the CDKN2B gene that has been shown to be aberrantly expressed in various tumours and diseases." (PMID 37761946, 2023). "A study confirming the occurrence of LOH most frequent on chromosome 9 found four patients with biallelic deletion 9p21.3 (three of them had LOH) of the tumor suppressor gene cluster (CDKN2A, CDKN2BAS1, CDKN2B, and DMRTA1), which is fully consistent with our research." (PMID 40805197, 2025). "LncRNA CDKN2B-AS1 (CDKN2B antisense RNA1, also named as ANRIL), a 3.8-kb-long RNA, transcribed from the short arm of human chromosome 9 on p21.3, was significantly up-regulated in stage I LUAD tissues compared to adjacent non-tumor tissues, which was consistent with the published article." (PMID 28881680, 2017).
cardiovascular disease (39 papers, 2014 to 2025). "Genetic variation of the lncRNA ANRIL (CDKN2B-AS1) first highlighted the potential role of lncRNAs in cardiovascular disease." (PMID 36806681, 2023).
intestinal vascular diseases (2 papers, 2017 to 2025). "Rs7575840 in 6.5kda upstream of ApoB gene, rs11591147 in PCSK9 gene and rs9644862 in the CDKN2B-AS1 (or named ANRIL; p15AS; PCAT12; CDKN2BAS; CDKN2B-AS; NCRNA00089) gene were illustrated to mostly influence the risk of intestinal vascular diseases." (PMID 39991491, 2025).
metabolic disease (2 papers, 2018 to 2020). A congenital disorder (due to inherited enzyme abnormality) or acquired (due to failure of a metabolically important organ) disorder resulting from an abnormal metabolic process. "ANRIL, also known as cyclin-dependent kinase inhibitor 2b-antisens RNA 1 (CDKN2b-AS1), also emerges as an actor in several metabolic diseases." (PMID 32971832, 2020).
CDKN2B-AS1 also shares sentences with these, for which no sentence is quoted: melanoma (38 papers); breast carcinoma (26); glioma (26); Stroke (21); hepatocellular carcinoma (19); ischemic stroke (19); colorectal cancer (18); cervical cancer (16); leukemia (14); nasopharyngeal carcinoma (14); ovarian carcinoma (12); bladder cancer (11); Obesity (11); pancreatic cancer (11); thyroid cancer (11); colon carcinoma (10); endothelial dysfunction (10); non-small cell lung carcinoma (10); cerebral infarction (7); Hypertension (7); lymph node metastasis (7); plexiform neurofibroma (7); retinoblastoma (7); acute myeloid leukemia (6); acute myocardial infarction (6); Alzheimer disease (6); diabetic retinopathy (6); esophageal squamous cell carcinoma (6); liver cancer (6); basal cell carcinoma (5).
A further 146 diseases each share a sentence with CDKN2B-AS1 in 5 papers or fewer.